TAAR2 (trace amine associated receptor 2)
Description:
Orphan olfactory receptor specific for trace amines. Trace amine compounds are enriched in animal body fluids and act on trace amine-associated receptors (TAARs) to elicit both intraspecific and interspecific innate behaviors. Ligand-binding causes a conformation change that triggers signaling via the G(s)-class of G proteins which activate adenylate cyclase.
Synonyms: TaR-2; GPR58
Tractability: Small molecule: it belongs to a druggable protein family. Antibody: UniProt places it where antibodies can reach, with medium confidence; UniProt predicts a signal peptide or a membrane-spanning region; its Gene Ontology location is reachable by antibodies, with medium confidence.
Target class: Monoamine receptor; Trace amine receptor; Membrane receptor; Family A G protein-coupled receptor; Small molecule receptor (family A GPCR)
Gene: Protein-coding gene on chromosome 6 (132,617,022 to 132,624,275, reverse strand). Ensembl gene ENSG00000146378.
Subcellular location: Cell membrane
Pathways (Reactome):
Signal Transduction: Amine ligand-binding receptors; G alpha (s) signalling events
Gene Ontology:
Molecular function: G protein-coupled receptor activity; trace-amine receptor activity
Biological process: G protein-coupled receptor signaling pathway
Cellular component: plasma membrane; membrane
Genetic constraint (gnomAD): Loss-of-function variants: 30 observed, 26.59 expected, observed/expected ratio (o/e) 1.13, 90% interval 0.84 to 1.53. The upper end of that interval is the gene's LOEUF score, 1.53, which puts it in group 6 of 6, group 1 being the genes least tolerant of losing a copy. Missense variants: 481 observed, 437.61 expected, observed/expected ratio (o/e) 1.1, 90% interval 1.02 to 1.18. Synonymous variants: 150 observed, 150.09 expected, observed/expected ratio (o/e) 1, 90% interval 0.87 to 1.14.
Homologues: Orthologues: chimpanzee TAAR2P (97% identical), macaque TAAR2 (91% identical), guinea pig TAAR2 (85% identical), mouse Taar2 (84% identical), rat Taar2 (84% identical), rabbit TAAR2 (83% identical), pig TAAR2 (79% identical). Paralogues in human: TAAR1 (45% identical), TAAR5 (38% identical), TAAR9 (36% identical), TAAR6 (35% identical), TAAR8 (33% identical), HTR4 (28% identical), HRH2 (25% identical), HTR1A (24% identical), HTR1D (24% identical), DRD4 (23% identical), DRD1 (23% identical), DRD5 (22% identical), and 13 more.
Diseases named in the same sentence as TAAR2 in open-access papers:
TAAR2 is named in the same sentence as 10 diseases in open-access papers, as found by Europe PMC text mining. Sharing a sentence is not in itself a finding about the gene and the disease. The quoted sentences say what the papers report.
breast carcinoma (1 paper, 2019). "Indeed, higher expression of TAAR1, TAAR2, TAAR4, TAAR5, TAAR8 (in ER- cases) and TAAR9 provided better survival in breast cancer." (PMID 30718646, 2019).
irritable bowel syndrome (1 paper, 2018). Irritable bowel syndrome (IBS) is a chronic functional condition of the lower gastrointestinal (GI) tract characterized by abdominal pain or discomfort and disordered bowel habit (diarrhea, constipation, or fluctuation between the two). "Here, in an unbiased microarray screen, TAAR2, TAAR5, and TAAR9 were found to be among the most highly upregulated genes in biopsies from inflamed regions of CD patients, and contributed to the separation of CD patients from those with irritable bowel syndrome." (PMID 30013475, 2018).
melanoma (1 paper, 2022). A malignant, usually aggressive tumor composed of atypical, neoplastic melanocytes. "It is notable that, while TAAR1 and TAAR2 expression in melanoma was below the cut-off value, genes involved in the “Olfactory transduction pathway,” coupled with these receptors in nevi were retained in melanoma samples." (PMID 35053262, 2022). "Essentially undetectable TAAR1, TAAR2, and TAAR5 expression levels were observed in melanoma samples." (PMID 35053262, 2022). "Differential expression analysis demonstrated the drastic decrease of TAAR1, TAAR2, TAAR5, TAAR6, and TAAR8 expression in melanomas compared to benign nevi with only TAAR6, TAAR8, and TAAR9 remaining detectable in malignant tumors." (PMID 35053262, 2022).
Parkinson disease (1 paper, 2022). A progressive degenerative disorder of the central nervous system characterized by loss of dopamine producing neurons in the substantia nigra and the presence of Lewy bodies in the substantia nigra and locus coeruleus. "With regard to TAAR2, particularly intriguing would be a further detailed investigation of the mechanism by which TAAR2 can affect dopamine transmission and evaluation of the potential of future TAAR2-based therapies for the treatment of Parkinson’s disease." (PMID 35431833, 2022).
cancer (3 papers, 2018 to 2023). A tumor composed of atypical neoplastic, often pleomorphic cells that invade other tissues. "Also, it cannot be ruled out that the identified difference in the expression of TAAR2 and TAAR5 mirrors the loss of cancer-promoting pathways in tumor stroma." (PMID 37759760, 2023). "We estimated TAARs’ (including TAAR1, TAAR2, TAAR5, TAAR6, TAAR8, and TAAR9) associations with BC stage, grade, and molecular subtypes in these data and identified that the expression of all TAARs was associated with more unfavorable cancer subtypes, including basal-like and HER2-positive tumors." (PMID 37759760, 2023). "RNAseq data from 12 published cancer studies obtained from cBioPortal detected RNA for TAAR1, TAAR2, TAAR5, TAAR6, TAAR8, and TAAR9 in various cancers." (PMID 29997511, 2018).
bacterial infection (1 paper, 2024). "The joint activation of TAAR1 and TAAR2 stimulates neutrophil migration, which could indicate an important role of these receptors in the primary immune response, for example, in response to bacterial infection." (PMID 38672247, 2024).
tumorous (1 paper, 2023). "The overlap between genes co-expressed with TAARs in primary tumors and metastatic lesions is significant, and we found correlations between the expression levels of TAAR1, TAAR2, TAAR5, TAAR8, and TAAR9 and genes associated with neuroactive ligand signaling in both kinds of neoplasms." (PMID 37759760, 2023). "Currently, the expression pattern of TAARs in CAFs remains undiscovered, and immune-cell-infiltrating tumors seem to be the most probable source of TAAR mRNA, including TAAR2 and TAAR5 in tumor stroma." (PMID 37759760, 2023). "The identified differences in TAAR2 and TAAR5 expression levels between tumor cells and stroma seem to be reproducible in different groups, including inflammatory cancer, whilst tumorous and stromal cells demonstrate similar expression levels of TAAR1, TAAR6, and TAAR8." (PMID 37759760, 2023).
TAAR2 also shares sentences with these, for which no sentence is quoted: cardiomyopathy (1 paper); Hyperglycemia (1); renal carcinoma (1).